PRMT5 (protein arginine methyltransferase 5)
Diseases named in the same sentence as PRMT5 in open-access papers (continued):
Sharing a sentence is not in itself a finding about the gene and the disease.
breast carcinoma (continued). "To explore whether PRMT5 inhibition induces cytoprotective autophagy, we knocked out PRMT5 using CRISPR/Cas9 gene editing in multiple breast cancer lines and evaluated autophagy activity." (PMID 37400460, 2023). "The exosomal circRHOT1 may promote breast cancer progression by regulating the miR-204-5p/PRMT5 axis." (PMID 37924099, 2023). "Thus, PRMT5 is an actionable therapeutic vulnerability in breast cancers of this genotype and potentially fill an unmet need for patients with acquired resistance to CDK4/6i." (PMID 37502925, 2023). "Interestingly, preclinical studies showed that breast cancer cells display diverse sensitivity to PRMT5 inhibitors with triple negative breast cancer (TNBC) cells generally being relatively resistant." (PMID 37400460, 2023). "Thus, our data establish a foundation for treatment of breast cancer with combinatorial inhibition of PRMT5 and autophagy." (PMID 37400460, 2023). "Our work suggests PRMT5 inhibitors could be used in combination with chemotherapy or PARP inhibitors to treat ovarian or breast cancers, including in genetically proficient tumors through the induction of chemically induced synthetic lethality." (PMID 37861290, 2023). "Our results demonstrate that circRHOT1 could promote breast cancer development by targeting miR-204-5p/PRMT5 axis." (PMID 37924099, 2023). "PRMT5 is overexpressed and activated in various human cancers, including breast cancer." (PMID 37173967, 2023). "MTAP loss is associated with ER-, HER2- and TNBC status, features a distinctive GL with potential to impact both targeted and immunotherapies and enables emerging clinical trials testing MTA2 and PRMT5 inhibitors for patients with clinically advanced breast cancer." (PMID 36913304, 2023). "Moreover, Western blot showed that PRMT5 expression levels were increased in breast cancer patients and MCF-7 cells." (PMID 37924099, 2023). "Previous studies from our group also demonstrated that PRMT5 could reduce doxorubicin sensitivity in the treatment of breast cancer by inhibiting RNA m6A methylation." (PMID 35563196, 2022). "Further exploring the methylation status of cytosolic and other nuclear PRMT5 substrates may help us to better understand the implication of PRMT5 in breast cancer." (PMID 36230689, 2022). "Our previous work found that the FDA-approved drug tadalafil could act as a novel PRMT5 inhibitor and suppress tumor growth in breast cancer; we aimed to verify whether tadalafil could be used in colorectal cancer treatment." (PMID 36474242, 2022). "Our study revealed that PRMT5 and LSD1 are synchronously expressed in breast cancer patients and synergistic inhibition of PRMT5 and LSD1 significantly slows down the breast tumor growth and metastasis, providing a novel promising therapeutic strategy for patients with metastatic breast cancer." (PMID 35655230, 2022). "Therefore, finding suitable PRMT5 inhibitors to improve the sensitivity of chemotherapy drugs is of great significance for clinical breast cancer treatment." (PMID 35563196, 2022). "Our group previously identified tadalafil as a new PRMT5 inhibitor that effectively improves the sensitivity of tumor cells to doxorubicin and other chemotherapeutic drugs in breast cancer, providing new insights into breast cancer treatment." (PMID 35563196, 2022). "In terms of histone methylation, PRMT5 is a representative target for breast cancer therapy." (PMID 35743249, 2022). "In breast cancer cells, PRMT5 functions in various mechanisms." (PMID 35563196, 2022). "Finally, the anti-breast cancer effects of PRMT5 inhibitor A and its ability to enhance chemosensitivity were further verified in a xenograft mouse model." (PMID 35563196, 2022). "Importantly, PRMT5 and LSD1 are coordinately expressed in breast cancer patients and pharmacologic perturbation of both PRMT5 and LSD1 shows a synergetic effect on the inhibition of breast tumor growth and metastasis in vivo." (PMID 35655230, 2022).
breast carcinoma (continued). "This is a prominent challenge for targeting PRMT5 in breast cancer treatment." (PMID 35563196, 2022). "As a member of the arginine methyltransferase (PRMTs) protein family, PRMT5 mediates the methylation of protein and plays an important role of the progress in various cancer such as lung cancer, liver cancer, colorectal cancer, and breast cancer." (PMID 34745388, 2021). "Additionally, in breast cancer cells, PRMT5 is phosphorylated at T139 and 144 by LKB1, and the mutation of these sites leads to a significant decrease in PRMT5 catalytic activity and reduces the interaction with its co-factors—MEP50, pICln, and RiOK1." (PMID 34685445, 2021). "Furthermore, depletion of PRMT5 significantly inhibited breast cancer cell proliferation and tumor growth in mouse model." (PMID 34103528, 2021). "To investigate whether elevated levels of PRMT5 regulate WNT/β‐CATENIN proliferative signalling in breast cancer, we checked expression of all three WNT/β‐CATENIN pathway target genes in MCF7, HCC1937 and BT549 cell lines." (PMID 33462997, 2021). "Further studies using more breast cancer cell lines and mouse models are required to demonstrate whether PI3KCA mutations dictate the efficacy of PRMT5 inhibitor." (PMID 34103528, 2021). "The role of PRMT5 in breast cancer cell migration was studied by Boyden chamber assay." (PMID 33462997, 2021). "Along these lines, PRMT5 recruitment to the FOXP1 promoter facilitates FOXP1 expression via PRMT5-dependent H3R2me2s with concomitant WDR5/SET1/MLL complex-driven H3K4me3, implicated in maintenance of stemness in breast cancer stem cells (BCSCs)." (PMID 32743345, 2020). "However, the results of early clinical trials of PRMT5 are still worthy of attention, that is, this target has great prospects and possibilities in the treatment of breast cancer." (PMID 33193750, 2020). "Recently, PRMT5 has also been shown to methylate a key stemness factor KLF4 in breast cancer." (PMID 31694585, 2019). "It is possible that the expression of the PRMT5 gene in pulmonary epithelial cells represents the first step in the promotion of the occurrence of lung adenocarcinoma and can promote proliferation in breast cancer cells." (PMID 30704408, 2019). "However, immunohistochemistry analyses reveal that PRMT5 is differentially localized in TNBC compared to other breast cancer subtypes and to normal breast tissues." (PMID 30957988, 2019). "Importantly, TNBC exhibit a distinctive PRMT5 subcellular distribution, with significantly lower levels of nuclear PRMT5 than healthy breast tissues and all other breast cancer subtypes." (PMID 30957988, 2019). "In lung squamous cell carcinoma and breast carcinoma cells, protein arginine methyltransferase 5 (PRMT5) complexes with MEP50/WDR77, and WDR5 is recruited by the protein complex to target gene promoters, resulting in histone H3K4 trimethylation, target gene transcription and cancer cell invasion." (PMID 30488017, 2018). "Taken together, these results imply that PRMT5 has multiple roles in breast cancer growth, regulating both tumor-initiating and more differentiated cells, and that drug targeting of PRMT5 could potentially affect the survival of both cell populations." (PMID 29262329, 2017). "Given the development of pre-clinical small molecules targeting PRMT5, combination treatment of PRMT5 inhibitors, along with conventional chemotherapy enabling tumor de-bulking, could have a significant impact on long-term outcomes for breast cancer patients." (PMID 29262329, 2017). "Furthermore, high levels of PDCD4 and PRMT5 expression in breast cancer were correlated with poor patient outcome." (PMID 27556302, 2016). "Thus, increased levels of PRMT5 and KLF4 are highest in tissues from breast cancers associated with poor prognosis." (PMID 26420673, 2015). "Indeed, PRMT5 has been found to be overexpressed in leukemia, lymphoma, lung cancer and breast cancer." (PMID 26078354, 2015).
breast carcinoma (continued). "Coexpression of PRMT5 with programmed cell death 4 (PDCD4) influences tumor suppressor properties of PDCD4 resulting in accelerated tumor growth in a murine orthotopic model of breast cancer." (PMID 23202904, 2012). "Similarly, in breast cancer models, tamoxifen induces nuclear translocation of the PRMT5/MEP50 methylosome complex, where it catalyzes ERα methylation and promotes the recruitment of corepressors, such as SMRT and HDAC1, leading to the suppression of ERα transcriptional activity." (PMID 40919714, 2025). "Additionally, there are indications that PRMT5 may alter immune resistance in breast cancer and exhibit an inverse correlation with antitumor immunity in melanoma." (PMID 41463372, 2025). "In addition, in breast cancer models, PRMT5 inhibitors foster anti-tumor immunity." (PMID 39996755, 2025). "Notably, PRMT5 has been implicated in mediating doxorubicin resistance in breast cancer, suggesting that combining PRMT5 inhibitors with chemotherapy could synergistically suppress breast cancer cell proliferation and growth." (PMID 40791817, 2025). "Indeed, in a breast cancer xenograft model, PRMT5 depletion led to a 12-fold reduction in BCSCs." (PMID 39695328, 2025). "Furthermore, we tested whether ER+ breast cancer cells with low RB expression are sensitive to inhibition of PRMT5." (PMID 38480701, 2024). "Protein arginine methyltransferase 5 (PRMT5), an important arginine methyltransferase linked to tumor initiation and progression, has been reported to promote ferroptosis resistance in TNBC while impairing ferroptosis resistance in other breast cancer subtypes." (PMID 39614322, 2024). "Hence, we propose that the combination of ER and PRMT5 inhibitors can synergistically block the G1-to-S transition in ER+/RB-deficient breast cancer, independent of the CDK4/6/Cyclin D1 complex." (PMID 38480701, 2024). "However, the relationship between circRHOT1 and PRMT5 in breast cancer remains unexplored." (PMID 37924099, 2023). "Hence, we propose that the combination of ER and PRMT5 inhibitors can synergistically block the G1-to-S transition in ER+/RB-deficient breast cancer, and this effect is independent of the CDK4/6/Cyclin D1 complex." (PMID 37502925, 2023). "In addition, circ-PRMT5 acts as a miR-509-3p sponge to promote breast cancer." (PMID 35220397, 2022). "PRMT5, as an oncogene, plays an indispensable regulatory role in the pathological progression of several human malignancies, including lung, gastric, breast cancer, lymphoma, leukemia and glioblastoma, by depositing symmetric di-methylation marks on the arginine residues of substrates." (PMID 35624451, 2022). "However, the role of PRMT5 in breast cancer remains underexplored." (PMID 33462997, 2021). "Thus, PRMT5 is considered as a potential therapeutic target for breast cancer." (PMID 34103528, 2021). "We next examine whether PRMT5 inhibitors suppresses breast cancer cell proliferation." (PMID 34103528, 2021). "Moreover, PRMT5 was also reported to regulate drug sensitivity in breast cancer cells." (PMID 33193750, 2020). "In addition, PRMT5 is highly expressed in human breast cancer." (PMID 23202904, 2012). "In summary, we demonstrated that PRMT5 is upregulated and promoted EMT and invasion under hypoxia in breast cancer." (PMID 41150697, 2025). "We found a significant upregulation in PRMT5 gene and protein expression under hypoxia in both MCF7 and MDA-MB231 breast cancer cell lines." (PMID 41150697, 2025). "Again, protein levels of PRMT1/PRMT5 were generally higher in ES cells compared to MCF7 and SUM159 breast cancer lines." (PMID 40823091, 2025).
breast carcinoma (continued). "This is especially significant for breast cancer patients as MTAP deletion, a trait conferring synthetic lethality with single agent second-generation PRMT5 inhibitors is rarely observed." (PMID 39695328, 2025). "This study shows that PRMT5 regulates TCF3 alternative splicing under hypoxia and that this promotes EMT and invasion of breast cancer cells." (PMID 41150697, 2025). "Collectively, our results indicate PRMT5-mediated symmetric arginine dimethylation of histones regulates alternative splicing of TCF3 gene thereby enhancing EMT and invasion in breast cancer hypoxia." (PMID 41150697, 2025). "In this study, we have reported that PRMT5 is upregulated under hypoxia via CTCF, and its upregulation is essential for EMT and invasion of hypoxic breast cancer cells." (PMID 41150697, 2025). "Our study confirms at several levels that SHTN1 and KIF5B interact with both PRMT5 and RELA in luminal A breast cancer cells." (PMID 38417630, 2024). "MS4322 effectively reduced PRMT5 protein levels in the estrogen receptor (ER) + breast cancer cell line MCF-7 in concentration-, time-, PRMT5-, VHL-, and proteasome-dependent manners." (PMID 39614393, 2024). "PRMT5 and WDR77 are upregulated in a number of human cancers, including breast cancer, pancreatic cancer, glioblastoma, and lung cancer, and associated with poor survival, underscoring their essential role in oncogenesis." (PMID 39594744, 2024). "This interaction enhances the methyltransferase activity of PRMT5, leading to increased AKT phosphorylation activation and promotion of breast cancer cell proliferation." (PMID 39499734, 2024). "Both PRMT5 and TRAF6 are frequently overexpressed in various types of human cancers, including breast cancer, colorectal cancer, gastric cancer." (PMID 37173967, 2023). "Expression of protein arginine methyltransferase 5 (PRMT5) is highly positively correlated to DNA damage repair (DDR) and DNA replication pathway genes in many types of cancer cells, including ovarian and breast cancer." (PMID 37861290, 2023). "In breast cancer, SLUG forms a complex with LSD1 and protein arginine methyltransferase 5 (PRMT5), which facilitates cancer invasion." (PMID 37370762, 2023). "Our study provides preliminary evidence to show that a combination of PRMT5 and TRAF6 inhibitors achieves a better anti-proliferative effect in breast cancer cells." (PMID 37173967, 2023). "Alongside PRMT5, SNRPDI regulates the cell cycle through the M checkpoint and has been tied to lung and breast cancer." (PMID 38132437, 2023). "To discover actionable vulnerabilities in this refractory breast cancer subtype, we performed a genome-wide CRISPR screen using ER+/RB1-knockout (RBKO) cells and identified protein arginine methyltransferase 5 (PRMT5) as a novel dependency in these cells." (PMID 37502925, 2023). "Additionally, to further confirm whether circRHOT1 promotes breast cancer progression through the miR-204-5p/PRMT5 axis, we overexpressed PRMT5 in MCF-7 cells and then treated the cells with exosomes derived from MCF-7 cells transfected with si-circRHOT1 or si-NC." (PMID 37924099, 2023). "In this context, we describe the in vitro and in vivo utility of combining preclinical and clinical stage PRMT5 inhibitors with PARP inhibitors and standard-of-care chemotherapies for the treatment of ovarian and breast cancers." (PMID 37861290, 2023). "PRMT5 inhibitor molecules like GSK332659513, PRT81114 and JNJ-6461917815 are currently under investigation in advanced solid malignancies including breast cancer." (PMID 36913304, 2023). "To provide evidence for this knowledge gap, we evaluated the sensitivity of breast cancer cells to a specific PRMT5 inhibitor, GSK3326595 that has been tested in a phase II clinical trial for breast cancer (NCT04676516)." (PMID 37400460, 2023). "Taken together, all data shows that exosomal circRHOT1 promoted breast cancer proliferation, invasion, metastasis, and EMT through regulation of the miR-204-5p/PRMT5 axis." (PMID 37924099, 2023).
breast carcinoma (continued). "Similar to PRMT5 and APE1, the downregulation of SUPT16H significantly sensitized a breast cancer cell line MCF7 to IR." (PMID 37887269, 2023). "In ERα-positive breast cancer, liver kinase B1 (LKB1) interacts with and phosphorylates PRMT5 at T132, T139, and T144 within the nucleus." (PMID 37928266, 2023). "In another study, researchers synthesized a novel compound that has the potency to inhibit PRMT5, disrupt the interaction of PRMT5 and KLF4, and suppress breast cancer development." (PMID 38136401, 2023). "Protein arginine methyltransferase 5 (PRMT5) is highly expressed in multiple types of cancer and reported to decreased the breast cancer cell response to doxorubicin." (PMID 38053093, 2023). "We show here evidence that PRMT5 inhibitors suppress DDR gene expression through epigenetic and AS mechanisms and enhance the sensitivity of ovarian and breast cancers to chemotherapy and PARP inhibitors in vitro and in vivo." (PMID 37861290, 2023). "For instance, programmed cell death protein 4 (PDCD4) is methylated at R110 by PRMT5 to inhibit its anti-tumor properties, and the co-expression of PDCD4 and PRMT5 generates a tumor-promoting phenotype in an orthotopic breast cancer model." (PMID 35216622, 2022). "We therefore surveyed publicly available gene-expression data in The Cancer Genome Atlas (TCGA) database to compare PRMT5 or LSD1 expression in normal human breast tissues and breast cancer specimens." (PMID 35655230, 2022). "To this end, we first test the correlation between the expression level of PRMT5 and LSD1 in 114 human breast cancer samples using immunohistochemical (IHC) analysis." (PMID 35655230, 2022). "TRAF4 upregulates PRMT5 expression in the nucleus, and PRMT5 forms a specific zinc finger structure with TRAF4, which plays an essential role in activating the NF-κB signaling pathway and promotes breast cancer cell proliferation." (PMID 35242717, 2022). "This comprehensive study explores the RNA and protein expression of the main PRMT5 protein partner, MEP50, in the different breast cancer subgroups." (PMID 36230689, 2022). "If the combined targeting of PRMT5 and LSD1 is clinically meaningful, then PRMT5 and LSD1 likely would exhibit similar expression pattern in breast cancer patients." (PMID 35655230, 2022). "Inhibition of expression of the arginine methyltransferase PRMT5 with simultaneous decrease in dimethylation of the H4R3 mark was also observed in lung and breast cancer cells after treatment with curcumin." (PMID 36300880, 2022). "Collectively, these data support the observation that expression pattern of PRMT5 and LSD1 is similar in breast cancer patients." (PMID 35655230, 2022). "In the human breast cancer MDA-MB-231 cell, PRMT5 and WDR77 show high expression and nuclear localization." (PMID 34513846, 2021). "PRMT5 directly binds to CAPG, and CAPG regulate STC-1 transcription by competing with PRMT5 to enhance breast cancer metastasis." (PMID 34513846, 2021). "In breast cancer, colorectal cancer, and prostate cancer cells, PRMT4, PRMT5, and PRMT7 and their mediated hnRNPA1 methylation and splicing isomerism can effectively promote the growth of cancer cells." (PMID 34603017, 2021). "In concordance, PRMT5 is reported to bind to the promoter of FOXP1 and enhance the number of CSC in breast cancer." (PMID 33193750, 2020). "For example, ADMA catalyzed by PRMT1 is involved in genes that activate cell proliferation in breast cancer, while SDMA catalyzed by PRMT5 inhibits genes of cell cycle progression." (PMID 32859239, 2020). "PRMT5 and its substrate-binding partner WDR77 regulate alternative splicing through methylation of ZNF326 in breast cancer." (PMID 32392182, 2020). "PRMT5 is another prominent member of PRMTs that catalyzes SDMA and results in suppressing downstream gene transcription, which induces stemness of breast cancer cells." (PMID 32859239, 2020).